TERT (telomerase reverse transcriptase)
Diseases named in the same sentence as TERT in open-access papers (continued):
Sharing a sentence is not in itself a finding about the gene and the disease.
thyroid cancer (245 papers, 2014 to 2026). "Mutations in the TERT gene (telomerase reverse transcriptase) are genetic alterations that have been associated with various types of cancer, including thyroid cancer." (PMID 39744583, 2025). "In differentiated thyroid cancers, the presence of TERT promoter mutations is linked to an increased risk of transformation to ATC." (PMID 40363930, 2025). "TERT promoter mutations are linked with aggressive thyroid cancer cell features, disease recurrence, and increased mortality." (PMID 40344620, 2025). "Alterations in TERT are implicated in the aggressiveness of thyroid cancer and are associated with worse patient outcomes, especially when they co-occur with alterations in BRAF or RAS genes." (PMID 40396891, 2025). "TERT promoter mutations are rare mutations in thyroid cancer, which inherently limits the number of available cases for analysis." (PMID 40940948, 2025). "Understanding the implications of TERT promoter mutations in thyroid cancer is essential for personalized treatment strategies, risk assessment, and improving clinical outcomes in individuals with PTC." (PMID 39744583, 2025). "Multiple studies suggest that the coexistence of TERT promoter mutations with BRAFV600E is linked to more aggressive thyroid cancer behavior, although the impact of TERT mutations in small differentiated tumors is still unclear." (PMID 41595456, 2025). "In thyroid cancer, TERT overexpression is linked to promoter mutations and epigenetic alterations, which collectively influence TERT transcriptional activity." (PMID 40362481, 2025). "While lncRNA dysregulation has been associated with thyroid cancer progression and telomerase regulation, limited data are currently available in the literature that relate specific changes in lncRNA expression to TERT promoter mutations." (PMID 41154428, 2025). "TERT promoter mutations are common in various cancers, including thyroid carcinomas, where they enhance the proliferative potential of BRAF—or RAS-driven clones." (PMID 40149275, 2025). "BRAF mutation, RAS mutation, RET/PTC rearrangement, PAX8/PPARγ rearrangement, and TERT promoter mutation, are among the major molecular indicators linked to thyroid cancer." (PMID 38501105, 2024). "Thyroid cancer, particularly papillary thyroid cancer patients with a poor prognosis, can also be caused by TERT promoter (TERTp) mutations in conjunction with BRAF mutations." (PMID 38819232, 2024). "TERT promoter mutations have been widely recognized for several years as promising novel diagnostic and prognostic genetic markers of differentiated thyroid cancer (DTC)." (PMID 38961252, 2024). "A worse prognosis is linked to aggressive forms of thyroid cancer that have mutations in the TERT promoter region." (PMID 38501105, 2024). "Mutations in the telomerase reverse transcriptase (TERT) gene promoter area are linked to worse prognoses and more aggressive forms of thyroid cancer." (PMID 38501105, 2024). "The associations between TERT methylation and clinical tumor behaviors and outcomes of thyroid cancer had been investigated by few preliminary studies with limited number of thyroid patients." (PMID 38313800, 2024). "In 2013, telomerase reverse transcriptase promoter mutations (TERT), C228T and C250T, were identified in thyroid cancer as mutually exclusive but independently powerful in thyroid oncogenesis." (PMID 38441247, 2024). "The most common genetic abnormality in advanced thyroid cancer is TERT promoter mutations, which were observed in 66% of cases." (PMID 38630010, 2024).
thyroid cancer (continued). "The combination of BRAF mutation with other gene mutations significantly increases the risk of thyroid cancer invading the thyroid membrane and recurrence, with TERT mutations being the most common co-occurring mutation." (PMID 38607456, 2024). "Previous studies had shown that TERT promoter mutation is one of the major contributors to the gene’s overexpression in thyroid cancer." (PMID 38313800, 2024). "TERT promoter mutations occur frequently in aggressive subtypes of thyroid cancer, including versions of differentiated thyroid carcinoma." (PMID 38501105, 2024). "Telomerase reverse transcriptase (TERT) promoter-mutated thyroid cancers are associated with a decreased rate of disease-free and disease-specific survival." (PMID 38441247, 2024). "TERT promoter mutations have been related to a higher rate of recurrence and mortality in thyroid carcinomas." (PMID 39363120, 2024). "Among the genetic alterations encountered in thyroid cancers of adults, TERT promoter (pTERT) mutations, particularly p.C288T and p.C250T, have shown an incidence of 5–25% in some series." (PMID 37046700, 2023). "Several previous studies have demonstrated the prognostic significance of TERT promoter mutations in thyroid cancer." (PMID 36984536, 2023). "Our analysis included 13 consecutive surgically resected thyroid cancers with TERT promoter mutations (either C228T or C250T) and 12 randomly selected surgically resected thyroid cancers with a wild-type TERT promoter." (PMID 36984536, 2023). "Predicting TERT promoter mutation is thus necessary for the prognostic stratification of thyroid cancer patients." (PMID 36984536, 2023). "Many studies have revealed that a TERT promoter mutation is a predictor of thyroid cancer aggressiveness." (PMID 36672362, 2023). "We detected an association between poorer prognoses and TERT promoter mutations when they coexist with other mutations, highlighting the supportive role of concurrent mutations in developing aggressive thyroid cancer." (PMID 36672362, 2023). "High-sensitivity screening for TERT promoter mutation status in thyroid cancer is possible through histologic analysis with the assistance of deep learning along with color transformation schemes." (PMID 36984536, 2023). "More recently, TERT promoter mutations (C250T and C228T) were discovered as strong oncogenic drivers in many types of thyroid cancer." (PMID 37859987, 2023). "A telomerase reverse transcriptase (TERT) promoter mutation can strongly predict thyroid cancer aggressiveness." (PMID 36672362, 2023). "-The clinical utility of BRAF, KRAS, NRAS, and TERT promoter mutation analysis on ctDNA appeared to be limited to early-stage thyroid cancers." (PMID 37762070, 2023). "A model based on histological subtype, TPO and NIS expression and TERT promoter mutation, all evaluated on initial surgical material, can predict iodine avidity in thyroid cancer tissue ahead of treatment." (PMID 37352166, 2023). "TERT promoter mutations are genomic abnormalities in thyroid cancer, and are reported to occur in 5–15% of PTC." (PMID 37544981, 2023). "Our findings showed that the likelihood of aggressive thyroid cancers was 10 times higher in patients with TERT promoter and other concurrent mutations." (PMID 36672362, 2023). "TERT promoter mutations have been repeatedly found in human cancer, particularly with high frequency in human melanoma and thyroid cancer." (PMID 36984536, 2023). "Materials and Methods: In this study, we evaluate TERT promoter mutation status in thyroid cancer through the deep learning approach using histologic images." (PMID 36984536, 2023). "The modified initial risk stratification system for differentiated thyroid cancer published in the American Thyroid Association (ATA) 2015 guidelines recommends using the TERT promoter mutation status, if available, to improve risk estimates." (PMID 36672362, 2023).
thyroid cancer (continued). "Further investigations are required to elucidate different prognostic role of the two dominant types of TERT promoter mutation, especially in research on thyroid cancer." (PMID 37948420, 2023). "In thyroid cancer, the presence of TERT promoter mutations determines the creation of new binding sites for a family of transcription factors, ultimately leading to an upregulation of telomerase transcription." (PMID 37761374, 2023). "Intratumoral heterogeneity is a well-known phenomenon in thyroid cancer, and TERT promoter mutation status can differ across distinct tumor areas." (PMID 36984536, 2023). "Background and objectives: Telomerase reverse transcriptase (TERT) promoter mutation, found in a subset of patients with thyroid cancer, is strongly associated with aggressive biologic behavior." (PMID 36984536, 2023). "On the basis of the general perspective of medical doctors, we designed a two-step cascaded architecture to predict the mutation status of the TERT promoter in thyroid cancer." (PMID 36984536, 2023). "As in other types of thyroid carcinoma, TERT promoter mutations in OCA are associated with more aggressive tumor behavior, distant metastasis, and tumor dedifferentiation including radioiodine refractory disease." (PMID 37399519, 2023). "TERT-p mutations are involved in the progression and aggressiveness of thyroid cancers and are more common in PDTC and anaplastic thyroid carcinoma than in differentiated thyroid carcinoma." (PMID 35892838, 2022). "We performed mutational analyses for BRAF and the TERT promoter in thyroid cancer patients who had undergone surgery at our institution since 2019." (PMID 36230856, 2022). "TERT promoter mutations (TPMs) are observed with increasing frequency according to the severity of thyroid cancer." (PMID 35053525, 2022). "In thyroid cancer, our study indicates that the methylation of TERT promoter is as prevalent as TERT promoter mutations among clinically aggressive tumours (50% vs. 45.7% respectively), although with less specificity for disease prognosis." (PMID 35979662, 2022). "Particularly in thyroid cancer, mutations in the TERT promoter are present in 73% of advanced disease histologies, the dedifferentiated carcinomas." (PMID 35979662, 2022). "Mutations in the TERT promoter region have been identified in several cancers, including thyroid cancer." (PMID 36230856, 2022). "Mutations in the TERT promoter have been identified in thyroid cancer, including in RET-rearranged thyroid cancer, but their association with disease progression has been unclear." (PMID 35510953, 2022). "TERT promoter mutations are associated with poorer overall survival of thyroid cancer, while the prognostic role of TERT has been seldom reported in OS." (PMID 35504036, 2022). "Hotspot mutations in the TERT (telomerase reverse transcriptase) gene are key determinants of thyroid cancer progression." (PMID 35053525, 2022). "Previous studies demonstrated a higher prevalence of TERT promoter mutations in aggressive thyroid cancer with poor clinicopathologic characteristics." (PMID 36230856, 2022). "Promoter mutations of the telomerase reverse transcriptase (TERT) gene have been suggested as an oncogenic event in various cancers, including thyroid cancer (TC)." (PMID 35326537, 2022). "TERT promoter mutations have been identified in ∼9% of papillary thyroid cancers and 40–73% of advanced thyroid cancers, where they are associated with a more aggressive clinical course." (PMID 35510953, 2022).
thyroid cancer (continued). "As a single tertiary center, mutational analyses for BRAF and TERT promoter in all thyroid cancer patients have been implemented in our institution since 2019." (PMID 36230856, 2022). "Promoter mutations of the telomerase reverse transcriptase (TERT) gene occur frequently in thyroid carcinoma (TC), including papillary (PTC) and anaplastic subtypes (ATC)." (PMID 35326537, 2022). "TERT promoter mutations occur preferably in certain malignancies, including thyroid carcinomas (TCs)." (PMID 35326537, 2022). "Numerous malignant cancers, including thyroid carcinoma, head and neck cancer, cervical cancer, and urothelial carcinoma, have been linked to elevated TERT expression." (PMID 36157228, 2022). "In this study, we refined risk prediction for thyroid cancer using TERT promoter mutations and WHO 2017 morphological classification to enhance CSS and DFS predictions." (PMID 34497362, 2022). "The unique oncogene duet of coexisting BRAF V600E and TERT promoter mutations is widely proven to be a robust genetic background promoting thyroid cancer aggressiveness." (PMID 35284335, 2021). "These TERT-related genetic aberrations have been implicated in thyroid cancer with particular prevalence in aggressive subtypes." (PMID 34702207, 2021). "TERT promoter mutations alone have 100% specificity and only 7.0% sensitivity due to its low overall presence in thyroid cancers." (PMID 34684168, 2021). "The most aggressive thyroid cancers, including PDTCs and ATCs, exhibited the highest frequencies of TERT promoter mutations; (II) C228T was found as the predominant mutation, and the presence of C228T and C250T was generally mutually exclusive." (PMID 33669363, 2021). "TERT promoter mutations have been found to be strongly associated with different pathological types of thyroid cancers and are considered as the biomarker to the preoperative diagnosis and prognosis of thyroid cancers." (PMID 34032581, 2021). "TERT promoter mutations increase in frequency with more aggressive thyroid cancer subtypes and advanced stages of disease." (PMID 34676499, 2021). "In a cohort study involving 393 patients with differentiated thyroid cancer, we incorporated the TERT mutational status into AJCC TNM staging 8th edition (TNM-8), proposing a new prognostic system, termed TNM-8T." (PMID 34208345, 2021). "TERT promoter mutations are important diagnostic and particularly prognostic markers for thyroid cancer." (PMID 32948110, 2021). "Evaluating TERT promoter mutations and patient outcomes has demonstrated that the mutation can be an independent factor in predicting thyroid cancer shorter disease-free survival." (PMID 33669363, 2021). "Since the current AJCC TNM-8 is insufficient to distinguish the risk of mortality in patients with differentiated thyroid cancer, a proposal for a new survival prediction model that includes the TERT promoter mutational state is required." (PMID 33562809, 2021). "We analyzed the HRs of six combinations of TNM-8 stage and TERT promoter mutation status after adjusting for sex and histologic type for thyroid cancer-related death with 10-year and 15-year CSS." (PMID 34208345, 2021). "Hotspot mutations in the core promoter region of the telomerase reverse transcriptase (TERT) gene have been well established to associate with aggressive clinical characteristics, radioiodine refractory, tumor recurrence, and mortality in thyroid cancer." (PMID 34221969, 2021). "Conversely, some of the prevalent malignant tumors, including breast cancer, prostate cancer, thyroid cancer, colon cancer, stomach cancer, and leukemia, exhibit occasional TERT promoter mutations." (PMID 34395278, 2021).
thyroid cancer (continued). "Limited data are available on the diagnostic utility of circulating tumor DNA (ctDNA) in early-stage thyroid cancers for BRAF, KRAS, NRAS, and TERT promoter mutations, which are known detectable markers for thyroid cancers." (PMID 33915745, 2021). "TERT promoter mutations are one of the most potent prognostic biomarkers in thyroid cancer, and it is well known that coexistence of the TERT promoter and BRAFV600E mutation exerts synergistic effects leading to poor prognosis." (PMID 34831001, 2021). "A number of genetic alterations, such as TERT promoter mutations, have emerged as important prognostic markers that define the most aggressive class of thyroid cancers." (PMID 32948110, 2021). "The presence of TERT promoter mutations is found in thyroid cancers, except in medullary thyroid cancer (MTC), suggesting its role in thyroid tumorigenesis and poor clinical outcomes such as recurrence and mortality." (PMID 33995657, 2021). "In thyroid cancer, TERT promoter mutations have been proposed as prognostic markers, associated with decreased disease-free survival." (PMID 33776938, 2021). "TERT promoter mutations readily occurred in invasive thyroid cancer and were a strong predictor of poor clinical outcomes in thyroid tumor." (PMID 35433709, 2021). "Hotspot mutations in the core promoter region of the telomerase reverse telomerase (TERT) gene are considered as the most frequent non-coding mutations in follicular-derived thyroid cancer." (PMID 34221969, 2021). "Somatic mutations in the TERT promoter have been detected in dozens of human cancers, including thyroid cancer." (PMID 33562809, 2021). "The two most common TERT promoter mutations occurring in thyroid cancer are located in the promoter region (chr: 5, 1,295,228 C > T (C228T) and 1,295,250 C > T (C250T))." (PMID 33572167, 2021). "Up to now, around 200 research articles have been published, which involved more than 15,000 patients who were subjected to analyses for thyroid cancer TERT promoter mutation statuses and clinical significance." (PMID 33669363, 2021). "The clinical utility of BRAF, KRAS, NRAS, and TERT promoter mutation analysis on ctDNA appears to be limited to early-stage thyroid cancers." (PMID 33915745, 2021). "Since 2019, our center has started the TERT promoter mutation test in surgically resected thyroid cancer tissue." (PMID 34070093, 2021). "Using such classifications, strong links have been found for a connection between genetic markers, for example, BRAFV600E and TERT promoter mutations, and radioiodine refractoriness in thyroid cancer." (PMID 34298840, 2021). "In 2013, using whole-genome sequencing, mutations in the promoter of the TERT gene have been described in melanoma and in other human cancers, among which thyroid cancer." (PMID 33572167, 2021). "Conversely, the ratio of TERT C228T mutation per TERT promoter mutations was reported to be high in thyroid cancer, but the frequency of TERT promoter mutations was lower than that in other types of cancer." (PMID 34395278, 2021). "Recently, it has been shown that promoter mutations in telomerase reverse transcriptase (TERT) gene are associated with a poor prognosis in thyroid cancer, especially with concurrent BRAFV600E mutation." (PMID 34070093, 2021). "Since then, many hospitals in Korea have begun performing TERT promoter mutation tests for thyroid cancer patients." (PMID 34070093, 2021). "The most frequent TERT mutation in thyroid carcinoma is the C228T mutation, and its prevalence is increasing with the increase of the level of aggressiveness being lower in the less aggressive PTC and very high in the more aggressive ATC." (PMID 33572167, 2021). "According to the literature, TERT promotor mutations seem to correlate with larger nodules and with more aggressive thyroid carcinomas (including well-differentiated and anaplastic thyroid carcinomas)." (PMID 34204172, 2021).